CXCR4 (C-X-C motif chemokine receptor 4)
Diseases named in the same sentence as CXCR4 in open-access papers (continued):
Sharing a sentence is not in itself a finding about the gene and the disease.
sarcoidosis (7 papers, 2009 to 2024). Sarcoidosis is a multisystemic disorder of unknown cause characterized by the formation of immune granulomas in involved organs. "Type 1 innate lymphoid cells serve as a diagnostic biomarker for sarcoidosis, and the CXCR4 inhibitor plerixafor, an FDA-approved drug, may provide a targeted treatment." (PMID 39225100, 2024). "Multiple immune cell types induced CXCL12/CXCR4 signaling in sarcoidosis, including Th1 T cells, macrophages, and ILCs." (PMID 39225100, 2024). "Compared with gene expression profiles of other inflammatory skin diseases, sarcoidosis induced the strongest global expression of CXCR4." (PMID 39225100, 2024). "We conclude that the increased expression of CXCR4 on sarcoidosis-activated immune cells improved cell migration toward CXCL12." (PMID 39225100, 2024). "Mechanistically, CXCR4 inhibition reduced sarcoidosis-activated immune cell migration, and targeting CXCR4 or total ILCs attenuated granuloma formation in a noninfectious mouse model." (PMID 39225100, 2024). "For example, here, among other genes, STAT1, IL10RA, and PTEN were underexpressed in sarcoidosis CD14 monocytes compared to controls while CXCR4, ATG12, HIF1A, CCR1, and IER3 were overexpressed, consistent with the effects of TGFB1 signaling." (PMID 33363531, 2020). "A significant increase in VEGF (P = .03) and CXCR4 (P = .03) mRNA levels has been also detected in sarcoidosis' patients when compared with healthy controls.Conclusions." (PMID 20169144, 2009). "A statistically significant increase has been detected in CXCR4 mRNA expression in sarcoidosis in comparison with healthy subjects (mean ± SD, 2.40 ± 1.02 versus 0.86 ± 0.64, P = .03, resp)." (PMID 20169144, 2009). "To test whether CXCR4 regulates sarcoidosis-activated immune cell function, we performed a migration assay with PBMCs isolated from healthy volunteers and patients with sarcoidosis." (PMID 39225100, 2024). "Meanwhile, the “hsa04060: cytokine–cytokine receptor interaction’ pathway, including the CCL4, CSF1R, CXCR4, FLT1, and IL7 genes, could be highly associated with immune regulation and is strongly suspected to be involved in the pathogenesis of sarcoidosis." (PMID 35860586, 2022). "However, given that CXCR4 can induce chemotaxis in T cells and B cells (both express higher levels of CXCR4), it is plausible that these immune cell subsets have a greater contribution to sarcoidosis." (PMID 39225095, 2024). "Administration of an approved CXCR4 inhibitor, plerixafor, inhibited the formation of pulmonary granulomas in mouse models, suggesting that such therapeutic intervention may be possible in patients with sarcoidosis." (PMID 39225095, 2024). "Multiple immune cell types in sarcoidosis-affected skin exhibited increased expression of TLS-specific pathways, including CXCL12/CXCR4 signaling." (PMID 39225100, 2024). "Finally, CXCL12/CXCR4, a third signaling pathway important for TLS formation, was strongly induced in both non–sarcoidosis- and sarcoidosis-affected skin." (PMID 39225100, 2024). "In progressing sarcoidosis, T-bet correlated with CCL5, CXCR4, and CXCR7." (PMID 26696750, 2015). "In this issue of the JCI, Sati and colleagues used single-cell RNA-seq (scRNA-seq) and spatial transcriptomics to determine that CXCR4 was highly and preferentially expressed in T cells, B cells, and type 1 innate lymphoid cells (ILCs) in sarcoidosis lesional skin relative to nonlesional skin." (PMID 39225095, 2024). "In addition, through a rigorous interrogation of candidate mutations in genes using available informatic data resources, we envisaged that the highly ranked hub genes among 30 immune-related candidate genes could also contribute to the pathogenesis of sarcoidosis, including CCL4 and CXCR4." (PMID 35860586, 2022).
seminoma (7 papers, 2013 to 2023). A radiosensitive malignant germ cell tumor found in the testis (especially undescended), and extragonadal sites (anterior mediastinum and pineal gland). "In our work, cases with exclusively CXCR4 nuclear immunoexpression were significantly more frequent in seminomas and significantly associated with better relapse-free survival." (PMID 32758242, 2020). "Thirty-three tumors (47.1%) showed both cytoplasmic/membrane and nuclear expression of CXCR4, while 30 tumors (42.9%, 21 seminomas and nine non-seminomas) had exclusive nuclear staining." (PMID 32758242, 2020). "We have independently looked at the expression of CXCL12 and CXCR4 in TGCTs (McIver SC, Loveland KL, Roman SD, Nixon B, Kitazawa R, McLaughlin EA, unpublished observations) and confirmed that CXCR4 mRNA was overexpressed in seminomas." (PMID 24555040, 2013). "CXCR4 expression in tumor cells was diffuse (90–100% of cells) in all but three (pure) seminomas." (PMID 32758242, 2020). "Exclusive nuclear immunoexpression (vs. other patterns) of CXCR4 significantly associated with seminoma histology (p < 0.001), absent vascular invasion (p < 0.001), absent rete testis invasion (p = 0.005) and absence of disease relapse (p = 0.049)." (PMID 32758242, 2020). "We were able to confirm that both CXCL12α and β caused cell migration in the seminoma cell line (TCam2) while no migration response was observed in the CXCR4 positive non-seminoma cell lines 833ke and NTera2/D1." (PMID 24555040, 2013). "This study identified a nanobody-drug-conjugate targeting CXCR4 as a putative therapeutic option for GCT, i.e. seminoma and yolk-sac tumors." (PMID 37996954, 2023). "As shown by diminished cell viability, enhanced apoptosis induction, and detection of mitotic catastrophes, we confirmed the cytotoxic efficacy of the CXCR4-NDC in CXCR4+-GCT cells (i.e. seminoma and yolk-sac tumor), while non-malignant CXCR4--fibroblasts, remained largely unaffected." (PMID 37996954, 2023). "Therefore the expression of CXCL12 and CXCR4 is more likely to be a better indicator of the possibility of seminoma metastasis rather than non-seminoma." (PMID 24555040, 2013). "However, the non-seminoma cell line 2102EP does not, which is not surprising, as this cell line does not express CXCR4." (PMID 24555040, 2013).
Thrombocytopenia (7 papers, 2014 to 2024). A reduction in the number of circulating thrombocytes. "CXCR4 antagonists are clinically used to support HSC mobilization and can improve therapy options in malignant conditions with thrombocytopenia." (PMID 33804965, 2021).
ulcerative colitis (7 papers, 2009 to 2026). An inflammatory bowel disease involving the mucosal surface of the large intestine and rectum. "Since it has been verified that the overexpression of ICAM-1 and CXCR4 can promote the homing of MSC in the treatment of ulcerative colitis, the overexpression of H19 exhibited therapeutic effects in ulcerative colitis." (PMID 34630738, 2021). "In summary, the overexpression of H19 in MSC downregulated miR-139 and miR-141, thus increasing the activity of their targets ICAM-1 and CXCR4, respectively, to exhibit therapeutic effects in ulcerative colitis." (PMID 34630738, 2021). "In studies of ulcerative colitis (UC), CXCR4 expression also showed a significant increase." (PMID 41481752, 2026). "Similarly, increased expression of CXCR4 on human PMNs was observed in colonic biopsies from people with active ulcerative colitis." (PMID 36712325, 2022). "Utilizing ulcerative colitis and apical periodontitis as inflammatory disease models, it is found that CXCR4/Cur‐CMVs are obviously aggregated within inflammatory areas after intravenous administration, which results in significant amelioration of ulcerative colitis and apical periodontitis." (PMID 34687286, 2021). "Further research suggested that high CXCR4 expression may be closely related to the migration of immature plasma cells to the inflammatory sites in UC, revealing the important role of CXCR4 in the pathogenesis of ulcerative colitis." (PMID 41481752, 2026).
anemia (6 papers, 2008 to 2023). A reduction in the number of red blood cells, the amount of hemoglobin, and/or the volume of packed red blood cells. "A multivariate analysis was carried out to assess the independence of the correlations between T-helper absolute count, age, requirement of IV treatment for iron-deficiency anemia and CXCR4 MFI ratio on T-helper cells, in the HHT group." (PMID 34906163, 2021). "In summary, we assessed whether HIV-1 env characteristics and CXCR4 co-receptor affinity were associated with the occurrence of severe anaemia in Malawian children." (PMID 18312662, 2008).
atrial fibrillation (6 papers, 2021 to 2025). A disorder characterized by an electrocardiographic finding of a supraventricular arrhythmia characterized by the replacement of consistent P waves by rapid oscillations or fibrillatory waves that vary in size, shape and timing and are accompanied by an irregular ventricular response. "Studies have shown that myocardial cells in atrial fibrillation display elevated CXCR4 expression and heightened inflammatory responses compared to controls." (PMID 39055656, 2024). "In the immune cell correlation analysis of atrial fibrillation feature genes, we observed that CXCR4 was negatively correlated with regulatory T cells and Macrophages M2, while LDHB was positively correlated with gamma delta T cells, and DPEP2 was positively correlated with CD8 T cells." (PMID 41359645, 2025). "Our qPCR validation further confirmed that SNAI2 and CXCR4 may be target genes of miRNA-613, and the expression level of these genes was significantly up-regulated in patients with atrial fibrillation, while miRNA-613 was significantly down-regulated in patients suffering from atrial fibrillation." (PMID 40549746, 2025). "AMD3100, the CXCR4 antagonist, can evidently reduce the contents of the inflammatory cytokines in the atria of atrial fibrillation (AF)‐modeled mice." (PMID 39295108, 2024). "In the atrial fibrillation dataset, LDHB, PFKFB2, CKAP4, CXCR4, DPEP2, and RORA genes showed an upregulation trend, while only the CD81 gene was downregulated in the disease group." (PMID 41359645, 2025). "In the selection of feature genes for atrial fibrillation, LDHB, DPEP2, BCL11B, CKAP4, RORA, PFKFB2, and CXCR4 were identified as potentially important predictors, with the model error being lowest when the number of genes reached eleven." (PMID 41359645, 2025). "CXCR4 and TYROBP may activate the PI3K/AKT pathway by promoting the expression of inflammatory indicators, further leading to the development of atrial fibrillation." (PMID 35607269, 2022). "CXCR4 and TYROBP might be involved in the development of atrial fibrillation by affecting inflammation‐related signalling pathways and may serve as targets for early diagnosis and preventive treatment." (PMID 35607269, 2022). "These experimental validations confirm the bioinformatics predictions and substantiate our hypothesis that the downregulation of miR-613 observed in atrial fibrillation patients could contribute to disease progression by relieving repression of SNAI2 and CXCR4 expression." (PMID 40549746, 2025).
bladder (6 papers, 2005 to 2021). "Immunocytochemistry, western blot, and affinity-purification analyses were used to study how androgens influenced the expression, subcellular localization, and function of CXCR7, CXCR4, and androgen receptor (AR) in LNCaP prostate-tumor cells." (PMID 25884570, 2015). "Prostate bone metastases, by contrast, express high levels of CXCR4 in both the nucleus and the cytoplasm." (PMID 15668715, 2005). "Former researches also showed that CXCL12/CXCR4 axis could regulate bladder carcinogenesis via activating extracellular signal-regulated kinase (ERK), which was subject to TXNIP negative regulation." (PMID 33747959, 2021). "In particular, overexpression of TXNIP attenuates CXCL12-induced bladder carcinogenesis, while knockout of TXNIP enhances CXCR4 expression in bladder carcinogenesis in urothelial cells, indicating an interaction may exist between TXNIP and CXCR4." (PMID 29386025, 2018). "Here we show that, in the LNCaP prostate-tumor cell line, androgens coordinate the expression of CXCR4 and CXCR7, thereby promoting CXCL12/CXCR4-mediated cell motility." (PMID 25884570, 2015). "Furthermore, MIF–CXCR4 interaction increases in experimental bladder inflammation, with PAR4-induced abdominal hypersensitivity shown to occur through MIF and at least partially also through CXCR4 on the urothelium." (PMID 26347749, 2015).
brain injury (6 papers, 2013 to 2025). Acute and chronic (see also brain INJURIES, CHRONIC) injuries to the brain, including the cerebral hemispheres, CEREBELLUM, and brain STEM. "Intravenous injection of CXCR4‐MSC can increase the amount of migration to the rat brain after resuscitation, promote behavioral recovery in rats, and improve the therapeutic effect of brain injury." (PMID 40984643, 2025).
depression (6 papers, 2017 to 2025). "Also, the administration of a CXCR4 receptor antagonist blocks a cocaine-induced increase in conditioned place preference and locomotor activity, and endogenous CXCR4 is positively associated with behaviors like locomotor activity and depression that are linked to excess consummatory behavior." (PMID 40806293, 2025). "This analysis exhibited several cytokines and receptors, including IL10, CXCL9, and CXCR4, as key components in the relationship between depression and immunotherapy efficacy." (PMID 40761787, 2025). "Six potential depression‐related target genes of miR‐511‐3p were identified: CXCR4, LBR, CPS1, VPS13B, COL9A3, and GABRB3." (PMID 41341504, 2025). "Moreover, the validation of the nodes or important proteins in the CXCR4 signaling pathways and the relation between the functional mechanism of the activated pathways and depression also need to be studied." (PMID 28293639, 2017). "It suggested that patients with higher percentage of CXCR4+ EPCs at 7 days after TBI presented obvious anxiety and depression." (PMID 28203485, 2017). "To date, the mechanisms responsible for the impact of antidepressants on the CXCL12–CXCR4 brain axis have not been studied in any animal model of depression, so further understanding of the fluoxetine signaling pathways downstream of CXCR4 will be crucial." (PMID 29163165, 2017).
experimental autoimmune encephalomyelitis (6 papers, 2009 to 2024). An autoimmune demyelinating disease of the central nervous system that is produced experimentally in animals by the injection of homogenized brain or spinal cord in Freund's adjuvant. "Evidence has shown that the NPC migration through white matter in experimental autoimmune encephalomyelitis was also based upon the CXCL12/CXCR4 signaling." (PMID 24771246, 2015). "With AMD3100, a specific antagonist of the CXCL12 receptor CXCR4, this hypothesis was tested in experimental autoimmune encephalomyelitis (EAE)." (PMID 39070795, 2024). "For example, CXCL12 polarizes CXCR4+ macrophages into IL-10-secreting M2-like macrophages and CXCR4+CD4+ T cells into IL-10-producing regulatory T cells (Tr1) that suppress experimental autoimmune encephalomyelitis (EAE)." (PMID 30320116, 2018). "Using the murine MS model, experimental autoimmune encephalomyelitis (EAE), we previously demonstrated that antagonism of the chemokine receptor CXCR7 blocks endothelial cell sequestration of CXCL12, thereby enhancing the abluminal localization of CXCR4-expressing leukocytes." (PMID 22145790, 2011).
hairy cell leukemia (6 papers, 2014 to 2025). Hairy cell leukemia (HCL) is a rare type of leukemia in which abnormal B-lymphocytes are present in the bone marrow, spleen and peripheral blood. "Hairy cell leukemia cells are characterized by high expression of receptors for molecules such as C-X-C chemokine receptor type 4 (CXCR4), very late antigen-4 (VLA-4), adhesion molecules including integrins and CD44, B cell antigen receptor (BCR), and CD40 antigen." (PMID 38882583, 2024).
hypogammaglobulinemia (6 papers, 2017 to 2025). "For instance, the use of CXCR4 antagonists, such as plerixafor and mavorixafor, to treat warts, hypogammaglobulinemia, infections, myelokathexis syndrome caused by GOF CXCR4 mutations results in significantly less wart and infection burden." (PMID 41608118, 2025). "Warts, hypogammaglobulinemia, infections, myelokathexis syndrome, in which the clinical manifestations include neutropenia, hypogammaglobulinemia, and mild to extensive warts is an AD immunodeficiency caused by gain of function mutations in the chemokine receptor CXCR4." (PMID 28894446, 2017).
keloid (6 papers, 2020 to 2026). An irregularly shaped, elevated mark on the skin caused by deposits of excessive amounts of collagen during wound healing. "Similar results have been reported in keloid tissue, with an increase in SDF-1 expression and CXCR4-positive cells in keloids compared to normal tissue." (PMID 33123623, 2020).
leukocytosis (6 papers, 2013 to 2023). "Early studies using Cxcr4- or Cxcl12-deficient mice established the importance of HSPC maintenance of leukocytosis." (PMID 36821386, 2023). "The bicyclam CXCR4 antagonist plerixafor (known in the literature as AMD3100) was originally developed to inhibit cell entry of HIV X4-strains via CXCR4; however, initial in vivo preclinical tests revealed a massive leukocytosis following plerixafor administration." (PMID 33980979, 2021). "Blocking CXCR4 with pharmacological agents disrupts CXCL12 signaling and leads to leukocyte release and increased white blood cell (WBC) count in peripheral blood (leukocytosis)." (PMID 29554149, 2018). "Administration of the CXCR4 antagonist AMD 3100 reversed this observation and led to a release of HSC progenitor cells from the bone marrow and fast generalized leukocytosis, demonstrating the importance of CXCL12 as a retention signal for HSC in the bone." (PMID 24040160, 2013). "Under diabetic conditions in mice, decreased Cxcl12 expression (not Cxcr4) determines the primitive hematopoietic maintenance in the BM niche and indirectly affects leukocytosis in the circulation." (PMID 36821386, 2023). "Moreover, CXCR4 is a prognostic marker that is independent of other classical factors such as age, leukocytosis, FLT3 mutant, and extramedullary infiltration." (PMID 31518054, 2019).